INS (insulin)
Diseases named in the same sentence as INS in open-access papers (continued):
Sharing a sentence is not in itself a finding about the gene and the disease.
diabetes (continued). "The clinical variables assessed were age, antihypertensive medication, BMI, duration of diabetes, glycated hemoglobin (HbA1c), insulin day dose, sex, smoking, systolic blood pressure, total cholesterol, and total triglycerides." (PMID 31540069, 2019). "Diabetes is a group of metabolic disorders characterized by hyperglycemia resulting from defects in insulin secretion, insulin action, or both." (PMID 31915541, 2019). "Type 2 Diabetes Mellitus (T2D) is a metabolic disorder characterized by an increase in circulating glucose levels, arising due to impaired insulin secretion and/or the resistance of peripheral tissue to insulin action." (PMID 31396158, 2019). "The clinical trial with type 1 diabetes mellitus (T1DM) subjects treated with the same fixed combination (Berberol®) showed decreasing of insulin dose necessary to reach adequate glycemic control." (PMID 31652576, 2019). "Diabetes mellitus (DM) has been recognized as a metabolic disorder which occurs due to failure of insulin secretion, insulin action, or both." (PMID 31514311, 2019). "Diabetes mellitus is one of the most encountered chronic and progressive metabolic disorders characterized by elevated levels of blood glucose due to the fact of insulin resistance or impaired insulin secretion." (PMID 31717650, 2019). "Median BG checking frequency ranged from 0.8 to 1.0 times per day depending on diabetes type and insulin use." (PMID 31593545, 2019). "This form of diabetes is observed when remaining functional β-cells are unable to produce insulin in sufficient amounts to compensate for the body’s insulin resistance." (PMID 31817135, 2019). "All factors interference with glucose homeostasis and insulin sensitivity promotes the development of diabetes." (PMID 31737070, 2019). "So insulin is of vital importance in controlling blood sugar, protecting β cells, preventing and delaying the occurrence of other diseases related to diabetes." (PMID 31257946, 2019). "Patients with type 1 or type 2 diabetes mellitus always require insulin therapy to control the blood glucose level every 2 or 3 times per day." (PMID 31257946, 2019). "Diabetes mellitus was found in 2 (2%) of the Somali women; one had metformin-treated type 2 diabetes, and body weight 106 kg, BMI 36.7 kg/m2 and the other had insulin dependent type I diabetes, 82 kg and BMI 30.1 kg/m2." (PMID 31057029, 2019). "Since NAFLD is often associated with insulin resistance, even though in a complex and bidirectional relationship, drugs increasing insulin sensitivity have been proposed to treat liver steatosis and prevent diabetes in these patients." (PMID 31010049, 2019). "Both groups were matched in terms of age, sex, the presence of diabetes requiring insulin therapy and exacerbations in the previous 12 months requiring treatment with intravenous antibiotics." (PMID 31208380, 2019). "The involvement of the pancreas in diabetes and the isolation of insulin were first achieved in pancreatectomised dogs." (PMID 31516543, 2019). "Effective diabetes management depends on the harmony of several factors, such as insulin treatment, eating habits, exercise and personal control." (PMID 30905141, 2019). "Recent studies have shown that combination therapies increase the levels of insulin and monoamines, reduce oxidative stress and production of proinflammatory cytokines, and can potentially be used to treat type 2 diabetes mellitus and co-morbid depression." (PMID 32082151, 2019). "As L44 mice developed obesity and diabetes despite high levels of amylin, insulin and leptin, they can be described as resistant to these hormones." (PMID 31601900, 2019). "Long-term adverse outcomes of ICIPI were chronic pancreatitis in three patients (4%) and diabetes in six (7%); five of them required insulin and the sixth required metformin." (PMID 30728076, 2019). "Diabetes mellitus is a prolonged metabolic disorder due to insufficient insulin production or an improper cell response to insulin." (PMID 30866459, 2019).
diabetes (continued). "Diabetes mellitus (DM) is a chronic metabolic disorder defined by hyperglycemia as a result of defects in insulin secretion (type 1 DM), insulin action (type 2 DM), or both (type 2 DM)." (PMID 31652638, 2019). "His postprandial C-peptide-to-glucose ratio was low at repeated measurements (mean, 0.21 × 10− 2 ng/mg or 1.26 × 10− 2 nmol/mmol), indicating that his diabetes was due to impaired secretion of insulin." (PMID 31630688, 2019). "Given that both DN and DR are characteristic microvascular complications of T2D, the results indicate that basal insulin supplementation benefits the microvascular complications of diabetes." (PMID 30973204, 2019). "One of the primary risk factors of LGA is poorly-controlled diabetes, particularly gestational diabetes, as well as pre-existing diabetes mellitus, which increase maternal plasma glucose and insulin levels, as well as stimulates fetal growth." (PMID 31801506, 2019). "The one patient diagnosed with insulin treated diabetes, 6 years after GD debut, was positive for ZnT8A, GADA, and IA-2A at GD diagnosis." (PMID 30783963, 2019). "Recently, a new protocol of efficient conversion of hESC into insulin-producing cells with the capability to promote a rapid reversal (2–6 weeks) of murine diabetes has been described." (PMID 30191384, 2019). "The estimated effect of insulin pen administration on health outcomes and comorbidities in patients with diabetes under insulin therapy (based on the MatchIt model)." (PMID 31461470, 2019). "The three main types of DM are as follows: Type 1 diabetes (T1D), also known as “insulin-dependent diabetes mellitus” (IDDM) or “juvenile diabetes”, is caused by the inability of the pancreas to produce sufficient insulin due to beta cell loss." (PMID 31671732, 2019). "In line with such an assumption, in the present study ketoacidosis was completely reversed after carbohydrate re-feeding, once the insulin concentration increased above baseline level." (PMID 30987297, 2019). "Due to its function in diabetes in the control the blood glucose levels, insulin is a life-saving drug." (PMID 31756981, 2019). "PIO, a peroxisome proliferator activated receptors-γ (PPAR-γ) agonist, is used in clinical practice to treat diabetes as an insulin-sensitizing drug." (PMID 31829402, 2019). "Current strategies to treat type 2 diabetes mellitus and hyperglycaemia include reducing insulin resistance, and supplementing with exogenous insulin or increasing endogenous insulin production." (PMID 30719284, 2019). "Even though a century after the invention of insulin, diabetes still calls for significant therapeutic measures." (PMID 31969896, 2019). "This study should be continued in future for the development of intestinal insulin producing drugs, to control diabetes under irreversible β cells damage." (PMID 31380261, 2019). "Diabetes is a common metabolic disease characterized by hyperglycemia resulting from defects in insulin secretion, insulin action, or both." (PMID 31132993, 2019). "Insulin is the mainstay of diabetes treatment, however, hypoglycemia remains a major obstacle in achieving good glycaemic control and fear of hypoglycemia can limit treatment intensification as a result of the patient’s unwillingness to take medication." (PMID 31584770, 2019). "Because the exercise effect is insulin-independent, it works well in patients with diabetes, too43–45." (PMID 31395858, 2019). "The importance of using autologous serum and not heterologous antigens (i.e., FBS serum) for antigen-loaded (insulin B9-23 and B15-23 peptides) tolDCs was clearly documented both by diabetes prevention and Tregs induction." (PMID 31139178, 2019). "It is difficult to evaluate the effect of executive functions on diabetes care and thus a patient's ability to count calories and insulin doses and adjust insulin to effort, and so on." (PMID 31183368, 2019).
diabetes (continued). "We were unable to investigate differences between radiation toxicity in insulin or medication using patients with diabetes because all of our patients used oral medications." (PMID 32231858, 2019). "Univariate analysis suggested that higher BMI, ASA, diabetes requiring insulin, use of a drain, choice of antiseptic for skin preparation and skin closure were associated with significant increase in SSI risk (p<0.05)." (PMID 30679297, 2019). "Knowledge and attitude of the respondents: the majority of the respondents had good knowledge regarding insulin self-injection (94.1%) and diabetes mellitus (82.8%)." (PMID 31692777, 2019). "Previous studies have demonstrated that preserved insulin sensitivity and low prevalence of diabetes are the metabolic peculiarities of centenarians, suggesting the possible role of adipokine homeostasis in healthy longevity." (PMID 30923512, 2019). "One possible explanation for the greater decrease in the glucose level in the DM group is that diabetes patients with a high insulin level can have increased sensitivity of IGF-I receptors." (PMID 30916168, 2019). "A total of 3120 patients undergoing insulin therapy for type 2 diabetes mellitus (T2DM) during 2000–2010 were enrolled." (PMID 30611254, 2019). "Accordingly, blood glucose management using CGM in patients with type 2 diabetes mellitus necessitates paying close attention to the insulin dose and changes in weight." (PMID 30775385, 2019). "This study aims at assessing the effects of advanced insulin pump system on patients with type 1 diabetes mellitus (T1DM)." (PMID 31183161, 2019). "With the C57BL/KsJ background, Lepob/ob mouse develops more severe hyperglycemia and diabetes, accompanied by increasing insulin levels, followed by β-cell failure, and often dies by 6 months of age." (PMID 30823474, 2019). "Patients with older age at onset,higher level of endogenous insulin and metabolic syndrome were more likely to beable to switch from insulin to other treatments for diabetes, in two studies on multiethnic groups in USA without comparatorsfrom elsewhere." (PMID 31673335, 2019). "Simultaneous islet autotransplantation (IATx) can prevent diabetes in 30–40% of patients and improve glycemic control with insulin supplementation in an additional 30% of individuals leading to improvement in quality of life in the majority of patients." (PMID 29159772, 2019). "The serum C-peptide level reflects insulin secretion from pancreatic islet cells and residual insulin secretion function and has been suggested as a useful parameter in classifying diabetes." (PMID 30682116, 2019). "Preserving the capacity of beta-cells to secrete insulin in line with changing demand is a key goal in diabetes management." (PMID 30642053, 2019). "Diabetes is defined as “a group of metabolic diseases characterized by hyperglycaemia resulting from defects in insulin secretion, insulin action, or both”." (PMID 31208038, 2019). "A higher proportion of patients in the STO group reported using more concomitant diabetes medications in addition to insulin compared with the V-Go group at EOS." (PMID 32685581, 2019). "Type 2 diabetes mellitus is characterized by insulin resistance in the metabolic pathway involving IR-B, with compensatory increase in the secretion of insulin (hyperinsulinemia)." (PMID 31354621, 2019). "In diabetes, both inappropriate glucagon secretion, which is attributed to alpha-cells, and impaired insulin secretion, which is attributed to beta-cells, contributed to hyperglycemia." (PMID 30646613, 2019). "Previous medical history included the placement of five coronary artery stents, type 2 diabetes mellitus for which he was placed on scheduled insulin, hypertension, and chronic kidney disease." (PMID 31431840, 2019).
diabetes (continued). "We found that HFpEF patients with diabetes, treated with insulin, had a higher median NT‐proBNP and evidence of more congestion than those not treated with insulin, despite their younger age and similar average LVEF and duration of HF." (PMID 31271255, 2019). "Thirty-four percent (30/87) of the males and 21% (13/63) of the females were being treated for diabetes with a stable regimen of antidiabetic medications (90% of diabetic males, 92% of diabetic females) or insulin (27% of males, 8% of females)." (PMID 31730007, 2019). "Most of the subjects in this review required patients with diabetes when recruiting in the hospital, while diabetic patients needed long-term medication or insulin treatment." (PMID 31798675, 2019). "The identified insulin access and affordability issues, if ignored, will further worsen the catastrophic public health crisis from diabetes." (PMID 31636912, 2019). "Patients who died during the follow-up were older and had significantly higher insulin resistance (HOMA-IR), serum levels of glucose, insulin, HbA1c, and average diabetes duration." (PMID 31316151, 2019). "Technology supporting diabetes self-management comprises methods of insulin delivery and equipment to check blood glucose levels." (PMID 31604437, 2019). "In the last few decades, the link between diabetes mellitus and AD has been recognized, sharing several common mechanisms, especially defective insulin signaling." (PMID 31126115, 2019). "Recent reviews related to diabetes generally recognized GCK plays an important glucose induced insulin release by β-cells but some suggest the complexity of the system requires additional glucose sensitivity." (PMID 30949058, 2019). "Diabetes mellitus (DM) is a metabolic disorder characterized by a high level of blood sugar (hyperglycemia), resulting from defects in insulin secretion or insulin action or both." (PMID 30934586, 2019). "Metabolic overload by saturated fatty acids (SFA), which comprises β-cell function, and impaired glucose-stimulated insulin secretion are frequently observed in patients suffering from obesity and type 2 diabetes mellitus." (PMID 31412623, 2019). "There were 7 patients in the GDM group, 16 in the pDM group, and 18 patients in the diabetes group who were undergoing insulin therapy during the time of this study." (PMID 31415573, 2019). "In particular, patients with specific loss-of-function PCSK9 mutations or polymorphisms had increased prevalence in pre-diabetes and diabetes as well as higher HOMA-IR index and insulin levels." (PMID 31672148, 2019). "With regards to diabetes mellitus and in particular human insulin as a predictor for carvedilol choice, evidence suggests a favourable effect of carvedilol on glycaemic control in diabetic patients when compared to metoprolol." (PMID 31391573, 2019). "Although the presence of autoreactive T-cells is initially low, their numbers gradually increase, due to the recognition of certain diabetes-specific autoantigens and become activated, initiating the elimination of insulin-producing beta cells." (PMID 31561568, 2019). "The first group of controls were 240 patients who presented with T1DM to the hospital during the study period and who developed diabetic ketosis or ketoacidosis at onset and required insulin treatment at the time of diabetes diagnosis." (PMID 31771625, 2019). "The present study demonstrates a potential novel crosstalk in β-cells between FFAR1 and the Akt-mTOR pathway, a major signaling pathway involved in insulin regulation and diabetes." (PMID 31426858, 2019). "Its link to insulin has made it a target for drug discovery for activators to increase insulin secretion in patients with diabetes." (PMID 31734826, 2019). "The method for calculation of insulin sensitivity has been described before in a high-ranking publication in patients with diabetes mellitus type 1, although at a blood glucose level of 90 mg/dl." (PMID 31536600, 2019).
diabetes (continued). "The cross-talk between NGF and insulin pathways downstream the insulin receptor suggests novel potential therapeutic targets to slow cognitive decline in AD and diabetes-related brain insulin resistance." (PMID 29736736, 2019). "Diabetes is characterized by hyperglycemia due to impaired insulin secretion and aberrant glucagon secretion resulting from changes in pancreatic islet cell function and/or mass." (PMID 30805033, 2019). "Diabetes mellitus, one of the oldest diseases known to man, is a common metabolic disorder characterized by chronic hyperglycemia due to impaired insulin secretion and/or its action." (PMID 31574903, 2019). "More patients with T1DM believed that the insulin dose calculator was the most important function of diabetes apps." (PMID 30735147, 2019). "Diabetes mellitus is a metabolic disease characterized by high levels of blood glucose resulting from defects in insulin secretion and/or insulin action." (PMID 31370156, 2019). "Clinical guidelines recommend that metformin be continued after insulin is initiated among patients with type 2 diabetes, yet little is known regarding how often metformin or other non-insulin diabetes medications are continued in this setting." (PMID 30759121, 2019). "Type 1 diabetes mellitus is characterized by the autoimmune destruction of the insulin-producing β-cells present in the islets of Langerhans, resulting in reduced insulin production." (PMID 35919481, 2019). "Perhaps the biggest game changer in current diabetes management is the ability to link sensor glucose readings to insulin delivery in sensor augmented and closed loop pump therapy." (PMID 31258513, 2019). "The link remains significant even after the adjustment for sex, diabetes duration, insulin dose, and HbA1c level." (PMID 31886290, 2019). "Editor's choice: Mild maternal hyperglycemia causes impaired glucose tolerance and metabolic alterations in wild-type neonatal offspring of INSC93S transgenic pigs, a novel large animal model for mutant INS gene-induced diabetes of youth (MIDY)." (PMID 31308048, 2019). "Insulin is the essential life-saver therapy for people with type 1 diabetes (7–10% of all diabetics)." (PMID 30754657, 2019). "NMN also mitigated diabetes-induced side effects including glucose intolerance and insulin signaling." (PMID 31823815, 2019). "In a second step, we divided diabetes medications into the five medication groups insulin, metformin, incretin, sulfonylurea and other diabetes medications, and analyzed them separately." (PMID 31238871, 2019). "The evidence from the present systematic review is insufficient to recommend the use of insulin analogs for all pregnant women with diabetes, due to the fact that the analyzed studies were classified as having a moderate or high risk of bias." (PMID 30786308, 2019). "Hypoglycaemia is a common side‐effect of diabetes therapies, particularly insulin, and imposes a substantial burden on individuals and healthcare systems." (PMID 30924567, 2019). "Such regulation of the Notch signalling pathway, in turn modulates the insulin signalling pathway and therefore, altered levels of miR-449a is critical in deregulated insulin signalling as seen during diabetes." (PMID 31345231, 2019). "It is believed that senescence represents a programmed phenomenon to facilitate β cell functional maturation and, therefore, senescence has been suggested to be involved in β cell regeneration, insulin secretion and diabetes development." (PMID 31721726, 2019). "Diabetes care continuously advances with new medical treatments, technical aids for insulin administration and the continuous monitoring of glucose levels, and skills facilitating self-management." (PMID 31412881, 2019). "Growing evidence suggests a role for L‐serine in the development of diabetes mellitus and its related complications, with L‐serine being positively correlated to insulin secretion and sensitivity." (PMID 31344283, 2019).